BMAL1 (basic helix-loop-helix ARNT like 1)
Diseases named in the same sentence as BMAL1 in open-access papers (continued):
Sharing a sentence is not in itself a finding about the gene and the disease.
Obesity (continued). "Obesity resulted in overall disruption of core clock genes (i.e., Bmal1, Clock, Rev-erbα/Nr1d1, Rev-erbβ/Nr1d2, Per1, Per2, Cry1, Cry2, Dbp and Rorα) in WAT." (PMID 35198059, 2022). "Next, we assessed the phosphorylation level of BMAL1 under nutrient-rich conditions using mice with high-fat diet (HFD)-mediated obesity." (PMID 35338256, 2022). "We found that adipocyte-specific overexpression of Bmal1 attenuated obesity and metabolic abnormalities." (PMID 35198059, 2022). "In the PVN of the hypothalamus, Gabrg2 protein has been implicated in diurnal rhythmicity in metabolism and diet-induced obesity through upstream regulation by the circadian gene Bmal1." (PMID 35215509, 2022). "We thus propose that PPAR-γ integrates obesity and adipocyte clock via epigenetic regulation of Bmal1, promoting a vicious cycle between circadian disruption and obesity development." (PMID 35198059, 2022). "Bmal1 ablation mice are prone to developing insulin resistance and an obesity phenotype by an alteration in glucose metabolism and impaired insulin signaling." (PMID 35111358, 2022). "It is thus proposed that BMAL1 is a fundamental factor linking obesity to circadian clock (adipocyte clock)." (PMID 35198059, 2022). "Supporting these findings, intestinal deficiency of Rev-erbα, a known BMAL1 repressor, enhances dietary fat absorption and exacerbates HFD-induced obesity and comorbidities." (PMID 34493722, 2021). "For instance, mice with BMAL1-KO in skeletal muscle resisted HFD-induced obesity due to increased oxidative capacity." (PMID 34831343, 2021). "Microglial-specific BMAL1-KO also prevented diet-induced obesity due to increased microglial phagocytic capacity." (PMID 34831343, 2021). "Obesity relocalizes BMAL1 occupancy genome-wide in omental adipocyte precursors, thereby altering the transcription of numerous target genes and contributing to metabolic inflammation." (PMID 33888702, 2021). "Intestine-specific deletion of Bmal1 in mice results in diet-induced obesity, that phenocopies intestine-specific knockout of and whole-body knockout of Dgat14,44." (PMID 34493722, 2021). "The agent metformin, an inhibitor of mTOR activity, can prevent such processes during obesity in experimental mouse models and can reverse the loss of SIRT1 function during inhibition of the circadian components CLOCK and BMAL1." (PMID 34590471, 2021). "Obesity also altered BMAL1 binding enrichment at additional targets, further reinforcing the concept of BMAL1 repositioning." (PMID 33888702, 2021). "The deletion of BMAL1 expression in the PVN at adulthood induces obesity and reduces circadian variation in corticosterone." (PMID 34960038, 2021). "Metformin, an inhibitor of mTOR, can protect SIRT1 activity to maintain proper circadian rhythm of CLOCK and BMAL1 during obesity." (PMID 34356626, 2021). "Further, obesity induced by a long-term high-fat diet was shown to increase the expression levels of core clock genes Bmal1, Dbp, and CK1ε in mouse livers and Bmal1, Clock, Per1/2/3, Cry1/2, Dbp, and CK1ε in the kidneys." (PMID 35156088, 2021). "Consistently, wild-type mice fed a HFD during nighttime (with a lower BMAL1 expression) show alleviated obesity compared to mice fed ad libitum." (PMID 34493722, 2021). "Obesity relocalizes BMAL1 occupancy genome-wide in human omental fat, thereby altering the transcription of numerous target genes involved in metabolic inflammation and adipose tissue remodeling." (PMID 33888702, 2021). "In a recent study, time restricted feeding has been shown to prevent obesity and improve metabolic function in whole-body Cry1;Cry2 knockout and in liver-specific Bmal1 and Rev-erba/b knockout mice." (PMID 33050331, 2020). "Intestinal lipogenesis also shows circadian variations, and hypertriglyceridemia and obesity are observed in Bmal1 knock out mice." (PMID 32365676, 2020).
Obesity (continued). "Here we show that deletion of BMAL1, a core clock gene, in paraventricular hypothalamic (PVH) neurons reduces diurnal rhythmicity in metabolism, causes obesity and diminishes PVH neuron activation in response to fast-refeeding." (PMID 32732906, 2020). "For example, disruption of Bmal1 leads to diabetes, obesity, abnormal gluconeogenesis, and lipogenesis." (PMID 32964049, 2020). "BMAL1 deletion diminished PVH neuron activation in response to fast–refeeding, reduces diurnal metabolic rhythmicity, and causes obesity development." (PMID 32732906, 2020). "Adipocyte-specific deletion of Bmal1 results in obesity in mice with a shift in diurnal rhythm of food intake and loss of circadian variation in plasma TG and glucose levels." (PMID 33050331, 2020). "Our present findings showing the regulation of metabolic capacity by BMAL1 in the skeletal muscle provide additional insight into the link between obesity/diabetes and the role of the molecular circadian clock systems in energy metabolism." (PMID 30231537, 2018). "In adipose tissue, deletion of the Bmal1 gene results in obesity with a shift in the diurnal rhythm of food intake." (PMID 30231537, 2018). "More recently, it has been shown that Bmal1 disruption in vivo actually leads to increased adipogenesis, adipocyte hypertrophy and obesity in global Bmal1 KO mice." (PMID 30374678, 2018). "Taken together, this study offered a mechanistic links between Bmal1 disruption, altered adipogenesis and development of obesity in mice." (PMID 30374678, 2018). "In contrast, knockdown of the Bmal1 gene was found to suppress adipocyte differentiation in 3T3-L1 cells, although in vivo studies have shown contradictory results, specifically, that mice with adipocyte-specific knockout of the Bmal1 gene develop obesity." (PMID 29518061, 2018). "The results demonstrated that the deletion of Bmal1 gene in the skeletal muscle prevents deposition of lipid and insulin resistance in obesity." (PMID 30231537, 2018). "Among several abnormalities, deletion of the clock gene Bmal1 in mice adipose tissue induces obesity." (PMID 25414671, 2014). "By contrast, over-expression of Bmal1 ameliorated metabolic fitness in diet-induced obesity." (PMID 39939483, 2025). "In addition, diet-induced obesity led to a relocation of BMAL1 DNA occupancy, thereby altering the rhythmic transcription of numerous genes involved in metabolic pathways, inflammation and matrix remodelling." (PMID 39939483, 2025). "Dysregulation of the BMAL1/CLOCK coupling may be the key to circadian disruption in the triggering of obesity and MetS." (PMID 40115347, 2025). "To determine whether the absence of p110α modifies core clock genes in the context of HFD-induced obesity, we assessed gene expression of Bmal1, Cry1, Per2, and Rev-erbα." (PMID 40228209, 2025). "Our Boolean model also revealed that obesity leads to down-regulation of key circadian genes, Bmal1 and Clock, which may impact several metabolic processes, including glucose homeostasis and insulin response." (PMID 40924721, 2025). "Additionally, the function of BMAL1 varies across different tissues; for instance, mice with intestine-specific BMAL1 knockout show resistance to obesity when fed a high-fat diet Further research is required to clarify this point." (PMID 39334848, 2024). "Visceral adipocytes isolated from women with obesity showed that during 24 h, Bmal1 expression changes in the first 12 h in visceral adipocytes compared with lean women, while Rev-reb and Cry2 expression is up-regulated during the 24 h in visceral and subcutaneous adipocytes." (PMID 39083072, 2024). "Therefore, the aim of the present study is to investigate the association between variants in candidate genes—namely, BMAL1 rs7950226 (G>A), CLOCK rs1801260 (A>G), CLOCK rs4864548 (G>A), and CLOCK rs3736544 (G>A)—and overweight/obesity in 291 pregnant women." (PMID 38612648, 2024).
Obesity (continued). "As a clock gene, the interference of Bmal1 has been revealed to increase adipogenesis and adipocyte hypertrophy via transcriptional control of Wnt pathway, providing a molecular link between circadian disruption and obesity." (PMID 37981207, 2023). "In addition, the use of the Arntl-floxed villin-Cre mice revealed that the epithelial expression of Bmal1 contributes to obesity development, body weight gain and related abnormalities, such as hyperlipidemia, through decreased lipid absorption." (PMID 35629894, 2022). "In a prior study, adipocyte-specific deletion of Bmal1 results in obesity in mice due to an attenuated rhythm in food intake (i.e., increased food intake in daytime) caused by temporal changes in circulating polyunsaturated fatty acids and in expression of neurotransmitters for appetite regulation." (PMID 35198059, 2022). "This suggests a crucial role of Bmal1 in connecting obesity to adipocyte clock machinery." (PMID 35198059, 2022). "To test this, we overexpressed Bmal1 in adipocytes in HFD-fed obese mice using recombinant adeno-associated virus serotype 8 (AAV8) vector encoding Bmal1 driven by an adipocyte-specific aP2 promoter (named “AAV8.aP2.Bmal1”), and examined its effects on obesity and associated comorbidities." (PMID 35198059, 2022). "Interestingly BMAL1 recruitment to target genes in adipose tissue is remodeled under conditions of obesity, a remodeling which can be reversed by nuclear factor kappa B (NF-κB) inhibition." (PMID 35631227, 2022). "The PubMed and Scopus databases were searched for studies reporting the association between circadian rhythm gene polymorphisms (ARNTL, BMAL1, CLOCK, CRY, PER, NPAS2, REV-ERBα, REV-ERBβ, and RORα) and MetS, and its comorbidities diabetes, obesity, and hypertension." (PMID 35053018, 2021). "Moreover, small-molecule targeting of REV-ERBα/BMAL1 by SR9009 ameliorates HFD-induced obesity in mice." (PMID 34493722, 2021). "Skeletal muscle BMAL1 and Per2 gene expression significantly increased after a 12-week exercise intervention in elderly with obesity and prediabetes Furthermore, skeletal muscle BMAL1 gene expression may improve insulin sensitivity." (PMID 34948558, 2021). "Given the critical role of REV-ERBα/BMAl1 in the development of HFD-induced obesity, it is of interest to test whether REV-ERBα/BMAL1 can be targeted to prevent this metabolic disorder." (PMID 34493722, 2021). "Moreover, intestinal deficiency of Rev-erbα, a known BMAL1 repressor, enhances dietary fat absorption and exacerbates HFD-induced obesity and comorbidities." (PMID 34493722, 2021). "Adipocyte O-GlcNAcylation may promote obesity through its well-established target clock proteins, such as BMAL1, CLOCK and PER2." (PMID 34557221, 2021). "The authors show that the clock gene BMAL1 drives paraventricular hypothalamic neuron activity via rhythmic GABAergic neurotransmission, and that this mediates diurnal metabolism and diet-induced obesity." (PMID 32732906, 2020). "BMAL1 subcellular localization and target recruitment was analyzed in several metabolically active peripheral tissues, including liver, muscle, and adipose tissue under conditions of diet-induced obesity." (PMID 29795456, 2019). "However, in HFD-fed offspring AUC for CLOCK and BMAL1 mRNA were lowest in offspring from obese dams indicated by a significant interaction of maternal obesity and HFD consumption (p<0.001)." (PMID 24416203, 2014). "Disruption of Bmal1 in mice led to increased adipogenesis, adipocyte hypertrophy, and obesity." (PMID 25414671, 2014). "Additional to the role of the Bmal1 gene in the cardiovascular system, the Bmal1−/− mouse model previously has been used for research regarding osteogenesis, myogenesis, insulin resistance and obesity." (PMID 25394423, 2014). "However, recently it was reported that disruption of Bmal1, in mice led to increased adipogenesis, adipocyte hypertrophy, and obesity, compared to wild-type mice." (PMID 24527263, 2012).
Obesity (continued). "Despite the fact that the regulation of metabolism by circadian clocks has been extensively studied, the destabilization of BMAL1 by adipsin highlights a novel potential mechanism of deregulation of circadian clocks in aging and obesity and how this may connect with metabolic dysfunction." (PMID 36394167, 2023). "Moreover, targeted inhibition of intestinal Bmal1 protects mice from HFD-induced obesity." (PMID 34493722, 2021). "Interestingly, the PVH exhibits BMAL1-controlled rhythmic expression of GABA-A receptor γ2 subunit, and dampening rhythmicity of GABAergic input to the PVH reduces diurnal rhythmicity in metabolism and causes obesity." (PMID 32732906, 2020). "In general, GF mice are resistant to HFD-induced obesity, produce lower levels of inflammatory cytokines including TNFα, IFNγ, IL-1B, and IL-17, and have blunted transcriptional oscillations of the core clock gene Bmal1 relative to conventionally-raised specific pathogen-free (SPF) mice." (PMID 33255707, 2020). "Thus, BMAL1-driven PVH neuron responsiveness in dynamic activity changes involving rhythmic GABAergic neurotransmission mediates diurnal rhythmicity in metabolism and is implicated in diet-induced obesity." (PMID 32732906, 2020). "Indeed adipocyte-specific deletion of Bmal1 exacerbates diet-induced obesity in mice." (PMID 23990898, 2013). "Abnormal expressions of PPP1CB and CSNK1E in obesity directly affect the core clock genes (PER1, PER2), and the accumulation of PERs and CRYs in the nucleus inhibits the transcription of CLOCK and BMAL1, disrupting energy homeostasis and leading to obesity." (PMID 39351493, 2024). "While BMAL1 is an essential partner in the circadian clock system, we chose to focus on the CLOCK gene because its impact on energy metabolism, obesity, and eating behaviors is more widely studied." (PMID 39744380, 2024). "In humans with obesity, 24-h gene expression of CLOCK, BMAL1, PER1, CRY2, and REV-ERBα in adipocytes is disturbed." (PMID 35111358, 2022). "We have shown that activation of intestinal REV-ERBα by SR9009 (a synthetic agonist) down-regulates BMAL1 expression in the intestine to reduce fat absorption and ameliorate HFD-induced obesity, providing a unique strategy for obesity prevention and control." (PMID 34493722, 2021). "Taken together, these data suggest a repressive role of BMAL1 on CCL2 transcription in OAPs, which is altered in obesity." (PMID 33888702, 2021). "Deletion of adipose tissue BMAL1 disrupted circadian clocks in adipocytes and exacerbated HFD-induced obesity through increasing food intake during daytime and reducing energy expenditure." (PMID 36994336, 2021). "By contrast, specific disruption of Bmal1 in the skeletal muscle prevents lipid deposition and HFD-induced obesity by increasing oxidative capacity." (PMID 34493722, 2021). "In insulin-resistant mice, the perturbation of CLOCK, BMAL1, reduced c-erb-αoncogene (REV-ERBα) and Cryptochrome Circadian Clock 1 (CRY1) mRNA expression is evident during obesity." (PMID 33142938, 2020). "While CLOCK expression levels are increased with HDF-induced obesity, peroxisome proliferator-activated receptor (PPAR) alpha increases the transcriptional level of brain and muscle ARNT-like 1 (BMAL1) in obese subjects." (PMID 31489938, 2019). "The 24 h pattern of clock genes showed that obesity alters the expression of CLOCK, BMAL1, PER1, CRY2 and REV-ERB ALPHA in adipocytes with changes found in CRY2 and REV-ERB ALPHA throughout the 24 h period." (PMID 25365257, 2014). "Hepatic mRNA expression of circadian (CLOCK, BMAL1, REV-ERBα, CRY, PER) and metabolic (PPARα, SIRT1) genes were strongly suppressed in offspring exposed to both maternal obesity and HFD." (PMID 24416203, 2014). "BMAL1 and CLOCK dysfunction leads to hyperphagia, obesity and metabolic syndrome including hyperlipidemia, hepatic steatosis, hyperleptinemia and hyperglycemia." (PMID 20706650, 2010).
Obesity (continued). "Other key genes in the circadian machinery, such as BMAL1, PER, CRY, and REV-ERB, are also crucial in regulating metabolic processes and have been shown to interact with pathological states like insulin resistance, diabetes, lipid metabolism, and obesity." (PMID 39744380, 2024). "On the other hand, obesity has also been reported to be associated with higher expression levels of Bmal1 in peripheral blood mononuclear cells, suggesting that the downregulation of Bmal1 expression due to u40Hz stimulation may result from metabolic improvements." (PMID 39334848, 2024). "BMAL1 knockout mice fed a high-fat diet were prone to obesity but did not develop insulin resistance." (PMID 37998747, 2023). "Mice lacking CRY1, CRY2, or liver-specific BMAL1 or REV-ERB genes were prone to obesity and gained weight rapidly with metabolic disturbances when fed a high-fat diet." (PMID 37998747, 2023). "In the study, the decreased expression of PPARγ in obese WAT trans-activates the uptake transporter Slc1a5; impaired PPARγ in obesity leads to the downregulation of SLC1A5 and decreased adipocyte uptake of glutamine and methionine (two epigenetic modulators), which disrupts Bmal1." (PMID 37626963, 2023). "Adipocyte-specific Bmal1 knockout leads to obesity, displaying the increase in food consumption when lacking Bmal1." (PMID 33808424, 2021). "BMAL1/CLOCK heterodimeric proteins are recognized as critical components of cellular circadian rhythm generation, which appear to be involved in liver disorders under obesity." (PMID 34943809, 2021). "Furthermore, deletion of BMAL1 in the PVN disrupts diurnal rhythms in metabolism and decreases neuronal response to refeeding, leading to obesity." (PMID 34831343, 2021). "Taken together, these results corroborate that REV-ERBα/BMAL1 plays an essential role in development of HFD-induced obesity and indicate that targeted inhibition of BMAL1 by REV-ERBα activation ameliorates HFD-induced obesity." (PMID 34493722, 2021). "Taken together, these data indicate that the microglia-specific Bmal1 knock-down protects mice from HFD-induced obesity, mostly by lowering energy intake without affecting many other global metabolic parameters (RER, physical activity, heat production)." (PMID 34050326, 2021). "Although it is unknown how Per1 and Per2 controls macrophage activation in obesity, the authors suggested a disruption in the feedback regulation of CLOCK/BMAL1 protein complex." (PMID 33371208, 2020). "By means of a mouse model in which BMAL1 is overexpressed specifically in β cells (β-Bmal1OV), they analyzed the effects of BMAL1 on glucose-stimulated insulin secretion (GSIS), islet transcriptomic and glucose metabolism in a diet-induced obesity context." (PMID 33371208, 2020). "Further research targeting the broader circadian molecular machinery, including genes like BMAL1, PER, CRY, and REV-ERB, may provide deeper insights into how circadian regulation affects metabolic diseases such as insulin resistance, diabetes, and obesity." (PMID 39744380, 2024). "In particular, rs7950226 (G>A) in the BMAL1 gene and rs1801260 (A>G), rs4864548 (G>A), and rs3736544 (G>A) in the CLOCK gene were reported to be significantly correlated with cardiovascular disease, obesity, metabolic syndrome, sleep reduction, and evening preference." (PMID 38612648, 2024). "A Western blot analysis of sWAT samples from normal-weight, obese, and weight-loss (WL) donors revealed that the BMAL2 protein was solely elevated by WL compared to BMAL1; demonstrating that BMAL2 is a WL-regulated adipogenesis inhibitor may aid in the development of strategies to combat obesity." (PMID 37626963, 2023). "For example, our data indicate that the expression of the vital clock component BMAL1 is not altered in the endothelium of obese mice, which could indeed cast doubt on the degree of circadian disruption present in obesity." (PMID 35600313, 2022).